SCN2A (sodium voltage-gated channel alpha subunit 2)
Diseases named in the same sentence as SCN2A in open-access papers (continued):
Sharing a sentence is not in itself a finding about the gene and the disease.
epilepsy (continued). "This variant was previously observed in an individual with a phenotype consistent with SCN2A-LOF-related epilepsy." (PMID 38251463, 2023). "A total of five cases of sudden unexpected death in epilepsy (SUDEP) occurred in patients with SCN1A, SCN2A, and SCN8A variants." (PMID 38174099, 2023). "We implemented OXC to treat three late-onset SCN2A-related epilepsy patients, and OXC was ineffective in one patient while seizures were completely controlled in the other two." (PMID 38174099, 2023). "Mutations in VGSCs (such as in SCN1A, SCN2A, SCN3A, and SCN8A) can lead to defects in inactivation gating, enhancing persistent sodium currents (INaP) and firing of neurons, resulting in epilepsy and ataxia." (PMID 40217485, 2023). "VGSCs are known to play an important role in neuronal excitability and epilepsies; especially mutations in VGSC subunit genes such as SCN1A, SCN2A, SCN3A, and SCN8A have been found to cause human epilepsies." (PMID 35860491, 2022). "Despite the highly similar electro-clinical phenotypes of the enrolled patients, the results obtained through NGS-based tests revealed possible variants in the SCN1A gene and four other epilepsy-related genes (SCN1B, SCN2A, SCN9A, and SCL2A1)." (PMID 35886038, 2022). "Multi-center, large-sample, and prospective studies are needed to further analyze the genotype–phenotype correlations of SCN2A-related epilepsy for precise medicine." (PMID 35431799, 2022). "This study investigated several genetic variants of SCN genes (SCN1A, SCN2A, SCN3A, SCN1B, SCN2B, SCN3B and SCN8A) and their association with epilepsy risk; these genes have been studied in this regard and conflicted results were reported." (PMID 35801810, 2022). "Epilepsy caused by the KCNQ2, KCNQ3, PRRT2, SCN2A and SCN8A gene are relatively benign with mild symptoms and consequences." (PMID 35571021, 2022). "The phenotypic spectrum of SCN2A-related epilepsy was broad, ranging from benign epilepsy in neonate and infancy to severe epileptic encephalopathy." (PMID 35431799, 2022). "In light of our finding, it seems more likely that the rs353139, rs16850331, rs12614399 of SCN2A found to influence the drug responsiveness to epilepsy." (PMID 35801810, 2022). "Although epilepsy caused by the KCNQ2, KCNQ3, PRRT2, SCN2A and SCN8A gene are relatively benign, in our study, more than 18 genes caused epilepsy accompanied by the intellectual disability and more than 14 genes caused syndromes with epilepsy." (PMID 35571021, 2022). "It has been suggested that SCBs are effective drugs in the treatment of epilepsy of patients with SCN2A variation." (PMID 35431799, 2022). "The large spectrum of SCN2A-related epilepsy includes epilepsy with a comparatively favorable prognosis and epileptic encephalopathy." (PMID 35886038, 2022). "The rs10182570 of SCN2A was correlated to Epilepsy classification (p = 0.039), while rs935403 was of the same gene found in association with seizure classification (p = 0.014)." (PMID 35801810, 2022). "Voltage-gated sodium channels (VGSCs) play a critical role in generation of action potentials, SCN1A, SCN2A, SCN3A, SCN8A and SCN1B have been identified to be associated with a spectrum of epilepsy phenotypes and neurodevelopmental disorders." (PMID 36006933, 2022). "In order of population prevalence, SCN1A, SCN2A, and SCN8A are the four voltage-gated sodium channel genes that are most commonly associated with epilepsy." (PMID 35250833, 2022). "We found that these variants, rs1965757, rs7581811, rs7592445 rs3943809, rs12614399 of SCN2A and rs7598098 of SCN3A imply variation of epilepsy risk depending on the individuals’ gender." (PMID 35801810, 2022). "We found that the rs10182570 of SCN2A was correlated to Epilepsy classification, whereas rs935403 of the same gene was found in association with Seizure classification." (PMID 35801810, 2022).
epilepsy (continued). "We will first consider therapies for SCN1A before addressing precision therapies for SCN2A/8A-related epilepsy because similar considerations regarding sodium channel blockade apply to these three conditions." (PMID 35250833, 2022). "In spite of past failed attempts in the use of ketogenic diets in managing SCN2A-seizures, ketogenic diet has proved successful in managing SCN2A-epilepsy when adopted early enough." (PMID 33841294, 2021). "KCNQ2 and SCN2A had both a concentration of EMR usage in the infantile period reflecting self-limited early onset epilepsies and a tail extending through childhood, reflecting DEE." (PMID 34031551, 2021). "Researchers have discovered that an impaired cortico-striatal excitatory transmission can trigger epilepsy among SCN2A haplodeficient mice." (PMID 34093402, 2021). "SCN2A (sodium channel, voltage-gated, type II, alpha subunit): 17 patients from 5 papers experience neonatal-onset epilepsy and subsequent MD." (PMID 33919646, 2021). "Genetic variants in the voltage-gated sodium channels SCN1A, SCN2A, SCN3A, and SCN8A are leading causes of epilepsy, developmental delay, and autism spectrum disorder." (PMID 34425903, 2021). "We included 413 unrelated individuals with SCN2A-related phenotypes in the final analysis: 392 from published literature and 21 from the Epilepsy Genetic Research Project at Children’s Hospital of Philadelphia." (PMID 33731876, 2021). "Sodium channel blockers have been avoided in SCN1A-related cases (loss-of-function variants) but preferred in early-onset SCN2A and SCN8A epilepsy (gain-of-function variants)." (PMID 33726816, 2021). "We should monitor the electroencephalogram regularly in the patients with SCN2A-related epilepsy even during their seizure-free period." (PMID 34093402, 2021). "It has been suggested that neonates with KCNQ2, KCNQ3 or SCN2a epilepsy respond well to treatment with low-dose sodium channel blockers, such as carbamazepine or oxcarbazepine." (PMID 33670692, 2021). "Previous studies have shown that Scn2a+/– ameliorates epilepsy in Kcna1–/– mice, improving survival, seizure characteristics, and brain–heart dynamics." (PMID 33484493, 2021). "Other epilepsy-causative genes, SCN1A and SCN2A, which encode the voltage-gated sodium channels type 1 and 2, respectively, have shown phenotypic differences based on variant types." (PMID 33262389, 2021). "Genetic loci associated with epilepsy (2q24.3) included two different sodium channel genes (rs6432860 in SCN1A and rs3769955 in SCN2A)." (PMID 33841294, 2021). "Although EEG has been used in SCN2A epilepsy patients to characterize neural dysfunction during seizures, it has not been used to measure brain activity in nonepileptic states." (PMID 32264956, 2020). "Though carbamazepine and high doses of phenytoin have been effective in some SCN2A epilepsy patients, many are refractory to these and other conventional antiepileptic drugs (AEDs)." (PMID 32244818, 2020). "The Chr2q24 linked region encompassed ~65 genes including the known epilepsy gene cluster (SCN1A, SCN2A and SCN3A)." (PMID 33216760, 2020). "Five different genes that encode alpha subunits of sodium ion channels have been reported to have mutations that lead to epilepsy; these include SCN1A, SCN2A, SCN3A, SCN8A, and SCN9A, and epilepsy-inducing mutations have also been reported in SCN1B." (PMID 33102526, 2020). "Some mutations of ion channels, such as SCN1A and SCN2A, are known to be associated with GEFS+, and some mutations of ion channels were also presumed to be associated with sudden unexpected death in epilepsy and cardiac arrhythmia." (PMID 33212914, 2020). "CSWS has been described in various genetic conditions, including common epilepsy-related ion channel genes like SCN2A or KCNQ2, as well as the N-methyl D-aspartate receptor subunit gene GRIN2A, that show overlapping expression at neuronal synapses." (PMID 33126500, 2020).
epilepsy (continued). "The most common diseases related with SCN2A mutation are West syndrome (WS; OMIM #308350), epilepsy of infancy with migrating focal seizures (EIMFS; OMIM #616645), and benign familial neonatal-infantile seizures (BFNIS; OMIM #607745)." (PMID 33013363, 2020). "Haploinsufficiency and polymorphisms of ANK3 and SCN2A in patients with ASD and epilepsy imply that AIS dysfunction is involved in the comorbidity of these diseases." (PMID 32641624, 2020). "NaV1.1 (SCN1A), NaV1.2 (SCN2A), NaV1.3 (SCN3A), NaV1.6 (SCN8A) and NaV1.7 (SCN9A) are genes whose mutations are related to epilepsy." (PMID 33013363, 2020). "Variants in epilepsy‐associated VGSC genes expressed in the central nervous system have also been associated with SUDEP: SCN1A, SCN2A, and SCN8A." (PMID 32449611, 2020). "In Scn2a haploinsufficient mice, we recently reported impaired excitatory transmission-dependent epileptic phenotypes mimicking later-onset milder epilepsies in ASD patients and impairments in learning/memory and replay of hippocampal place cells." (PMID 30962870, 2019). "Given that the predominant expression of Nav1.1 is in inhibitory neurons and that of Nav1.2 is in excitatory neocortical/hippocampal neurons, it seems reasonable that SCN1A loss- or SCN2A gain-of-function mutations lead to epilepsies." (PMID 30175250, 2018). "Mutant larvae of scn1lab, an ortholog of the ASD- and epilepsy-associated genes, SCN1A and SCN2A, exhibit spontaneous seizures (discussed in the “Epilepsy” section), as well as nighttime hyperactivity and increased thigmotaxis." (PMID 30210288, 2018). "However, it still remains unclear why SCN2A loss-of-function mutations also cause epilepsies." (PMID 30175250, 2018). "Biological prioritization implicates SCN1A, SCN2A, SCN3A, and TTC21B as the most likely genes underlying the signal at 2q24.3 for all epilepsy, focal epilepsy and genetic generalized epilepsy." (PMID 30531953, 2018). "Although a mutation in the sodium channel component has been demonstrated to induce epilepsy, the effect of altered SCN2A expression in epilepsy requires clarification." (PMID 24220630, 2014). "The cells, which had been transfected with the si-SCN2A vector, exhibited a repeated discharge, similar to that identified in epilepsy." (PMID 24220630, 2014). "Structural brain abnormalities appear to be more common in SCN-related epilepsies than previously recognized, particularly in SCN2A and SCN8A, where MRI changes may reflect both developmental disturbances and progressive injury." (PMID 41573391, 2025). "SCN2A-related epilepsy typically manifests in early childhood and spans a broad spectrum from self-limited epilepsy to severe early infantile epileptic encephalopathy, which can evolve into infantile epileptic spasms syndrome and LGS, primarily in cases associated with GOF variants." (PMID 40310132, 2025). "Although the precise upstream pathways driving CBD‐induced DEC2 expression require further elucidation, our findings suggest that enhancement of DEC2‐mediated SCN2A repression may represent an innovative therapeutic strategy for drug‐resistant epilepsy." (PMID 40641288, 2025). "Although this review documents gender distribution and reports genotype–phenotype associations, a detailed statistical analysis of the most frequent SCN2A variants among individuals with comorbid ASD and epilepsy, as well as formal testing of gender-specific trends, was not performed." (PMID 40507552, 2025). "As seen for other neuronal isoforms, variants in SCN2A have been associated with a broad spectrum of neurodevelopmental disorders, with or without epilepsy." (PMID 41515912, 2025).
epilepsy (continued). "In the same way, several DEEs caused by mutations in CDKL5, DNM1, KCNT1, SCN1A, SCN2A, SCN8A, and UBA5 genes, which present severe pharmaco-resistant epilepsy, are increasingly becoming targets for RNA molecules that aim to restore neuronal excitability and network function." (PMID 41244709, 2025). "Autism spectrum disorder and intellectual disability: Some loss-of-function mutations in Scn2a are associated with autism and developmental delays without severe epilepsy." (PMID 39452036, 2024). "For individuals with DEEs related to GOF variants in SCN2A and SCN8A, sodium channel blockers may be beneficial in the management of epilepsy; in contrast, with LOF variants in SCN2A and SCN8A, sodium channel blockers may worsen the epilepsy phenotype." (PMID 38540325, 2024). "Furthermore, another Chinese epilepsy cohort study demonstrated associations between SCN1A rs3812718 and SCN2A rs2304016 with VPA response." (PMID 38837984, 2024). "Pathogenic variants in voltage-gated sodium (NaV) channel genes including SCN2A, encoding NaV1.2, are discovered frequently in neurodevelopmental disorders with or without epilepsy." (PMID 37578743, 2023). "Because truncating SCN2A variants likely produce nonfunctional NaV1.2 channels, and because earlier studies of missense variants associated with epilepsy demonstrated gain-of-function (GoF), a general genotype–phenotype correlation emerged." (PMID 37578743, 2023). "SCN2A-related disorders, which manifest with epilepsy, autism, intellectual disability, or ataxia and chorea, may also involve dysautonomia." (PMID 36979316, 2023). "For example, KCNQ2, KCNQ3, SCN1A, SCN2A, and SCN8A are associated with phenotypes ranging from self-limited epilepsies with normal developmental outcome to intermediate severity conditions to drug-resistant epilepsies with profound developmental impairment." (PMID 37596007, 2023). "Specifically, evidence from in vitro functional evaluation of SCN2A variants supported the hypothesis that loss-of-function (LoF) variants were the drivers of ASD/ID, whereas GoF variants caused early-onset epilepsy." (PMID 37578743, 2023). "Sodium channel power-gated type II subunit (SCN2A) mutations are correlated with epilepsy, intellectual disability, and ASD without epilepsy." (PMID 36768153, 2023). "Indeed, we report for the first time post-operative seizure outcomes for six genetic causes of epilepsy: COL4A1, GRIN2B, NEXMIF, NSD1, SCN2A and SLC9A6." (PMID 37264783, 2023). "After searching in DrugBank, we retrieved a total of 47 anti-epileptic drugs and 151 targets, of which identified 17 target genes (CACNA1A, CHRNA4,CHRNA7,GABRA1,GABRA2,GABRB2,GABRG2,GRIK1,GRIN1,GRIN2B,KCNQ2,KCNQ3,SCN1A,SCN2A, SCN3A,SCN8A and SCN9A) were overlapped with risk genes of epilepsy." (PMID 36006933, 2022). "SCN2A and SCN1A, two genes detected in the current fetus, are known to be associated with epilepsy." (PMID 35819063, 2022). "Our results suggest that NP might be further explored to treat epilepsies which are sensitive to inhibition of voltage-gated sodium channels, including LGS where GOF mutations have been identified in SCN2A (NaV1.2) and SCN8A (NaV1.6) (Epi4K." (PMID 35689251, 2022). "A similar lack of association was seen in of SCN2A-associated disorders; those with epilepsy were similar to those without with respect to several medical morbidities that were assessed." (PMID 34517877, 2021). "Despite these promising results, mutation studies of SCN2A in patients with seizure disorders have not shown clearly defined phenotypes unlike SCN1A and SCN8A." (PMID 33841294, 2021). "Interestingly, status epilepticus during slow sleep (ESES), which aggravates cognitive impairment, has been found in SCN2A-related epilepsy." (PMID 34093402, 2021). "Both parents of our patient are heterozygous for the SCN2A variant but have neither epilepsy nor intellectual disability; and (iii) there are extensive phenotypic similarities with patient A, who does not carry this variant." (PMID 33938619, 2021).
epilepsy (continued). "SCN2A-related epilepsies identified in clinical patients through WES and/or NGS." (PMID 33013363, 2020). "Of the SCN2A mutations linked to autism, intellectual disability, and/or epilepsy, many of these variants appear to be de novo, rather than inherited." (PMID 32264956, 2020). "A total of three mutations were identified in known epilepsy genes (SCN1A, SCN2A)." (PMID 31439038, 2019). "Therefore, we performed qRT-PCR for Scn1a and Scn8a, coding for the voltage-gated sodium channels Nav1.1 and 1.6, as well as for the epilepsy gene Scn2a, coding for Nav1.2, in brain lysates from weaned and 5-month-old mice." (PMID 29046322, 2017). "In order to evaluate SCN2A as a candidate gene for epileptic susceptibility and the use of a Cu-Zn superoxide dismutase (SOD) supplement as a potential therapy for epilepsy, SCN2A expression in the cortex and the correlation between SCN2A and Cu-Zn SOD in SH-SY5Y cells were examined." (PMID 24220630, 2014). "However, the si-SCN2A vector group showed repeated discharge, which was similar to the phenomenon of epilepsy." (PMID 24220630, 2014). "On the other hand, since SCN2A mutations are linked to various forms of epilepsy, a late onset cannot be ruled out either." (PMID 24650168, 2014). "Among these genes, SCN2A has the most published evidence to support its role in the epilepsies." (PMID 24014518, 2013). "However, LOF SCN2A truncation can also occur in severe epilepsies including West syndrome and LGS." (PMID 41515912, 2025). "Polymorphisms in the SCN1A and SCN2A, genes associated with Dravet syndrome and febrile seizures were found with statistical significance in patients with FIRES indicating that an undiagnosed seizure disorder could be the cause." (PMID 40310164, 2025). "SCN2A variants have also been found in patients with autistic features in the absence of epilepsy." (PMID 38255008, 2024). "Furthermore, genes such as SCN3B, EPHA4, GABRB3, and SCN2A may play roles in the development of epilepsy in the context of AD." (PMID 38999445, 2024). "At present, voltage-gated sodium channel genes such as SCN1A, SCN2A, SCN3A, and SCN8A were reported to be causative genes of epilepsy, among them SCN2A has been reported to be the second most common, next only to SCN1A, the first reported causative gene for epilepsy." (PMID 35431799, 2022). "The functional impact of K905N, a variant associated with early-infantile SCN2A epilepsy, could not be resolved by either voltage clamp or DAPC." (PMID 35637276, 2022). "However, the epilepsy phenotypes and prognosis caused by SCN2A variation in Chinese children have not yet been studied in a large sample." (PMID 35431799, 2022). "In this study, meta-analysis was conducted to further explore the relationship between SCN1A and SCN2A gene polymorphisms and the efficacy of VPA in the treatment of childhood epilepsy, so as to provide etiological basis for individualized treatment of VPA in children with epilepsy." (PMID 34011048, 2021). "Moreover, our results highlight the importance of SCN2A mutational screening in cases of ID/ASD with or without epilepsy." (PMID 35053762, 2021). "Many SCN2A mutations leading to refractory epilepsies are often de novo rather than inherited." (PMID 33841294, 2021). "Qualitatively, the peptide overlap occurs in human proteins canonically associated with epilepsy such as gamma-aminobutyric acid receptor subunit alpha-1 (GBRA1), gamma-aminobutyric acid type B receptor subunit 1 (GABR1), sodium channel protein subunits (SCN1A, SCN2A." (PMID 24982805, 2014). "Thus, the upregulation of SCN2A expression in the cortex may be an effective treatment for the repeated discharge that occurs in epilepsy." (PMID 24220630, 2014). "Therefore, the present study provided a novel insight in to Cu-Zn SOD and its regulation by SCN2A in epilepsy; the decrease in SCN2A expression may reduce the concentration of Cu-Zn SOD in the brain cortex, which contributes to serious trauma to the cortex." (PMID 24220630, 2014).